BRCA2 (BRCA2 DNA repair associated)
Diseases named in the same sentence as BRCA2 in open-access papers (continued):
Sharing a sentence is not in itself a finding about the gene and the disease.
ovarian carcinoma (continued). "For example, the three BRCA founder mutations [BRCA1 185delAG (c.68_69del), 5382insC (c.5266dup), and BRCA2 6174delT (c.5946del)] have high carrier frequency (2.17%) in Ashkenazi Jewish population contributing to high risk of breast and ovarian cancer." (PMID 35595529, 2022). "Increased mortality due to ovarian cancer can be explained by shared inherited susceptibility genes such as BRCA1 or BRCA2, especially in young women." (PMID 36612726, 2022). "Germline mutations in breast cancer susceptibility gene 1 (BRCA1) and/or breast cancer susceptibility gene 2 (BRCA2) confer an increased risk of breast and ovarian cancers." (PMID 35918668, 2022). "BRCA1 and BRCA2 were shown to be susceptibility genes for ovarian cancer, and the BRIP1, RAD51C, rad51D and mismatch repair genes also play a role in this disease." (PMID 35910206, 2022). "The frequency of BRCA1 or BRCA2 gene mutation carriers among patients with ovarian cancer from the Podkarpacie region is comparable to other regions of Poland." (PMID 35382848, 2022). "BRCA1 and BRCA2 are the most commonly mutated BC susceptibility genes that convey a high-risk of breast and ovarian cancer and represent 25%–28% of hereditary BC." (PMID 36003761, 2022). "In some cases, tumors exploited NMD by positively selecting for nonsense mutations to downregulate tumor suppressor genes, as has been shown for BRCA1 and BRCA2, which were associated with inherited susceptibility and platinum resistance in ovarian cancer." (PMID 37223641, 2022). "Carriers of pathogenic variants in BRCA1 or BRCA2 are at significantly increased risk (Relative Risk (RR) > 4) for breast and ovarian cancer and this knowledge can guide screening for early detection and the use of risk-reducing prophylactic surgeries." (PMID 35665744, 2022). "For instance, female BRCA1 PV carriers are at a higher risk for breast and ovarian cancer than BRCA2 PV carriers." (PMID 36497436, 2022). "Determination of the BRCA1/BRCA2 mutation status in patients with breast and/or ovarian cancer is commonly performed using various molecular techniques." (PMID 35300046, 2022). "Most information on BRCA1 and BRCA2 mutations is tailored to women due to the availability of effective surgical risk reduction procedures for women’s breast and ovarian cancer." (PMID 35303741, 2022). "After the discovery of the BRCA1 and BRCA2 genes in the 1990s, the first guidelines for the care of high-risk individuals with hereditary breast and ovarian cancer stated that “there was insufficient evidence to recommend for or against prophylactic surgery”." (PMID 35805017, 2022). "This study is the first comprehensive bibliometric analysis of the top 100 most cited papers on BRCA1 and BRCA2 associated breast and ovarian cancer globally." (PMID 36197199, 2022). "Approximately 11% of unselected ovarian cancer patients in the region of Podkarpacie carry a BRCA1 or BRCA2 causative variants." (PMID 35382848, 2022). "BRCA1 and BRCA2 are the most frequently mutated genes in ovarian cancer (OC) crucial both for the identification of cancer predisposition and therapeutic choices." (PMID 36555431, 2022). "This explains the fact that individuals who have mutations in the BRCA1 and BRCA2 genes have an increased risk of developing different types of cancer, such as breast and ovarian cancers." (PMID 35805026, 2022). "The ALDH1A1 selective inhibitor NCT-501 can synergize with Olaparib to kill epithelial ovarian cancer cells carrying BRCA2 mutations." (PMID 36484016, 2022). "In the context of genetic testing in a woman with breast or ovarian cancer in which a mosaic BRCA1/BRCA2 pathogenic variant is found, it currently remains appropriate to discuss risk management options as for constitutional carriers." (PMID 36068545, 2022). "Previous studies proposed that mutations in BRCA2 exon 11 were closely related to breast/ovarian cancer risk and aggressiveness." (PMID 36292577, 2022).
ovarian carcinoma (continued). "Clinical BRCA1 and BRCA2 testing enables the identification of individuals at elevated risk for hereditary breast and ovarian cancer." (PMID 35918668, 2022). "Mutations in the tumor suppressor gene BRCA2 are associated with a predisposition to breast and ovarian cancers." (PMID 35950060, 2022). "Females that carry germline BRCA1 or BRCA2 pathogenic variants are at high lifetime risk of breast and ovarian cancer diagnoses, which can be 70% and 44%, respectively." (PMID 36358902, 2022). "Germline mutations in the BRCA1 and BRCA2 genes correlate in the development of most cases of hereditary breast and ovarian cancer." (PMID 36556118, 2022). "Although several founder mutations of the BRCA1 and BRCA2 genes have been reported, the breast and ovarian cancer risks varied by type and location of BRCA1/2 mutations." (PMID 35267543, 2022). "The initially described alterations involved BRCA1 and BRCA2 pathogenic variants (PVs), found in about 20–30% of ovarian cancers at diagnosis, urging the development of PARPi." (PMID 35158866, 2022). "In preclinical studies, PARP inhibitors showed antitumor effects not only in ovarian cancers but also on uterine sarcoma cell lines with BRCA2 gene mutations (SK-UT-1 and SK-UT-1B) in a concentration-dependent manner." (PMID 35267488, 2022). "Germline mutations in both BRCA1 and BRCA2 can, therefore, lead to a deficiency in the HR pathway and increase susceptibility to ovarian cancer." (PMID 35805770, 2022). "A previous study found that mutations in BRCA2 increase the risk of ovarian cancer by approximately 11.4%." (PMID 36397405, 2022). "This c.3860delA (p.Asn1287fs) BRCA2 pathogenic variant was previously reported in a Moroccan study in a patient suffering from ovarian cancer; however, in this study, it was detected in nine patients with BC family history." (PMID 36672847, 2022). "The cause of ovarian cancer is not well known, but there are relations between mutated BRCA1 and BRCA2 genes (genes which help in repair of DNA) and occurrence of ovarian cancer." (PMID 35877745, 2022). "In our previous study, we identified 10 of 158 (6.3%) of unselected cases of ovarian cancer from this region carried one of 13 founder mutations in the BRCA1 or BRCA2 genes." (PMID 35382848, 2022). "BRCA2 is an essential gene for DNA repair by homologous recombination and is often mutated in families at risk of breast and ovarian cancer." (PMID 35053516, 2022). "Altogether, in 18 of 158 (11.4%) ovarian cancer patients with BRCA1 or BRCA2 pathogenic mutations were found." (PMID 35382848, 2022). "The connection between the FA pathway and malignancy was evidenced when mutations in FANCD1/BRCA2, the breast/ovarian cancer susceptibility gene, had been detected in FA patients." (PMID 35330396, 2022). "Another identified BRCA2 pathogenic variant (c.9097delA) in this study was previously identified in North African breast/ovarian cancer patients in Tunisia." (PMID 36672847, 2022). "Since mutations in BRCA1 and BRCA2 were identified as major causes of ovarian cancer, the relationship between XBP1 and BRAC1/BRAC2 was individually analyzed." (PMID 35991556, 2022). "The present result was consistent with previous findings such as that ovarian cancer onset in BRCA2 mutation patients was an average 8-10 years later than in patients with BRCA1 mutation." (PMID 35205313, 2022). "It is notable that of the genes associated with gLOH and PARP response in ovarian carcinoma, only BRCA2 was associated with gLOH in this LMS cohort." (PMID 35468996, 2022). "This study retrospectively analysed the results of screening for genetic mutations of the BRCA1 and BRCA2 in breast and ovarian cancer patients among this population." (PMID 35918668, 2022). "BRCA1 and BRCA2 are the most well-studied and established genes in hereditary breast and ovarian cancer, while pathogenic variants in these genes are inherited in an autosomal dominant manner." (PMID 36358902, 2022).
ovarian carcinoma (continued). "For example, hereditary mutations of the BRCA1/BRCA2 genes in breast or ovarian cancer disable high-fidelity HRR of harmful DSBs." (PMID 36253861, 2022). "Most of the information on BRCA1 and BRCA2 pathogenic mutations are tailored to women due to the availability of effective surgical risk reduction procedures for breast and ovarian cancer among women." (PMID 35303741, 2022). "The epidemiologic evidence strongly supports a significant protective effect of oral contraceptive use on the risk of developing ovarian cancer among women with a BRCA1 or BRCA2 mutation." (PMID 35668475, 2022). "BRCA1 and BRCA2 mutations are known to contribute to the susceptibility of breast and ovarian cancers." (PMID 35740092, 2022). "Ovarian cancer patients with BRCA1 or BRCA2 mutations have a better response to platinum chemotherapy and longer progression‐free survival (PFS)." (PMID 38089758, 2022). "To date, three PARPis (olaparib, rucaparib, and niraparib) have been approved by the FDA for use in ovarian cancer patients with germline BRCA2 mutations." (PMID 36077694, 2022). "In conclusion, significant progress has been made in elucidating the role of BRCA1 and BRCA2 and their mutations in the risk and prognosis of epithelial ovarian cancer." (PMID 35147092, 2022). "DNA repair defects caused by BRCA1 and BRCA2 missense variants increase the risk of developing breast and ovarian cancers." (PMID 35729312, 2022). "Ovarian cancers with germline or somatic mutation of BRCA1 or BRCA2, mutation of RAD51C or RAD51D, methylation of BRCA1, or high LOH have all been reported to respond to PARP inhibition." (PMID 35223797, 2022). "Studies have shown that ovarian cancer cells with HR deficiency (with BRCA1 or BRCA2 mutations) have elevated sensitivity to PARP inhibition." (PMID 35267530, 2022). "Approximately 11–15% of all epithelial ovarian cancer (EOC) patients carry a BRCA1 or BRCA2 germline pathogenic variant (gPV)." (PMID 36137114, 2022). "While pathogenic mutations in genes such as BRCA1 and BRCA2 confer high risks of breast and ovarian cancers, these account for only a small proportion of all cancer cases in the general population." (PMID 35877228, 2022). "The IAP inhibitor LCL161 alone and in combination with a PARP inhibitor, exhibited antitumour effects in PDX mouse models of resistant BRCA2 and 1-mutated ovarian cancer, respectively." (PMID 35501389, 2022). "Loss-of-function variants in the BRCA1 and BRCA2 susceptibility genes predispose carriers to breast and/or ovarian cancer." (PMID 35665744, 2022). "In this article, we will review the existing epidemiologic evidence regarding the role of contraceptives and the risk of ovarian cancer with a focus on women with a BRCA1 or BRCA2 mutation." (PMID 35668475, 2022). "Defects in the HR pathway have been highlighted, mostly with loss-of-function mutations of BRCA1 and BRCA2, as germline mutations of these genes are significant risk factors for hereditary breast and ovarian cancers." (PMID 35163621, 2022). "BRCA1 was first described as a hereditary breast and ovarian cancer susceptibility gene in 1994, followed by BRCA2 in 1995." (PMID 36497436, 2022). "For women with BRCA1 and BRCA2 mutations, oral contraceptive use reduces the risk of ovarian cancer by 50% with a further 36% risk reduction for each additional 10 years of use." (PMID 35159349, 2022). "The major heritable risk factors for ovarian cancer (OC) are pathogenic germline variants in BRCA1 or BRCA2." (PMID 35456503, 2022). "Both BRCA2 variants (rs397507606 and rs397507402) were originally identified in a study of AA women with familial and early onset cases of breast and/or ovarian cancer." (PMID 36315513, 2022). "BRCA1 and BRCA2 inherited gene mutations, which greatly increase the risk of developing breast and ovarian cancers, are mutations that are frequently observed in hereditary breast and ovarian cancers (HBOC)." (PMID 35205313, 2022).
ovarian carcinoma (continued). "We therefore sought to determine the relationship between MAGEC3 and BRCA2 expression in ovarian cancer and their association with patient characteristics and outcomes." (PMID 36230652, 2022). "For examples, ovary cancer patients with BRCA1 or BRCA2 mutations benefit particularly from Poly ADP-ribose polymerase inhibitor Olaparib while solid tumors with MMR mutations have demonstrated high response rate to immune checkpoint blockade." (PMID 35273153, 2022). "In HRR pathway, germline or somatic BRCA1 and BRCA2 mutations are associated with increased risks of solid tumors, especially breast and ovary cancers." (PMID 35328658, 2022). "Pathogenic variants in BRCA2 cause genome instability and are associated with breast and/or ovarian cancers." (PMID 34356684, 2021). "EMSY amplification in sporadic breast and ovarian cancers resembles BRCA2 mutations in hereditary cancers in terms of the spectrum of pathology." (PMID 34440403, 2021). "Though BRCA1 and BRCA2 are most commonly associated with ovarian cancer as CPGs, several other CPGs have gained attention in recent years." (PMID 34070674, 2021). "Our studies show that the acquisition of Olaparib resistance in both BRCA-wildtype and BRCA2-mutated ovarian cancer cells is accompanied by increased STAT3 activity and pro-tumorigenic gene expression." (PMID 34956861, 2021). "Of note, heterozygous BRCA1 inactivation results in genomic instability in nontumorigenic breast epithelial cells, and heterozygous mutations in BRCA1 and BRCA2 have been shown to contribute to development of HGSC in an ovarian cancer mouse model." (PMID 33922503, 2021). "For example, germline mutations in BRCA1 and BRCA2 can increase the risk of developing many cancers with genomic instability, particularly breast and ovarian cancers." (PMID 34830134, 2021). "Pathogenic mutations of BRCA1 and BRCA2 genes are more frequent in ovarian cancer, but other genes are also related to this disease." (PMID 34547799, 2021). "PARP inhibitor maintenance therapy improves progression-free survival in BRCA2 germ-line deficient ovarian cancers." (PMID 33919707, 2021). "Having demonstrated that WRN complementation partially rescued the hyper-degradation phenotype of BRCA2-depleted cells, we tested the effect of WRN knockdown on nascent DNA degradation in the BRCA2-mutated ovarian cancer cell line PEO137." (PMID 34772932, 2021). "Among the FPC cohorts, ATM (3.09%) and BRCA2 (2.61%), two genes associated with breast and ovarian cancer, had the highest prevalence of PVs followed by CDKN2A (2.24%), the major high-risk susceptibility gene involved in familial melanoma." (PMID 34255164, 2021). "The value of BRCA1 and BRCA2 testing for cancer risk reduction in breast and ovarian cancer is well-established." (PMID 34072979, 2021). "This study aimed to evaluate the prevalence and spectrum of 13 BRCA1 and BRCA2 founder mutations most frequently observed in the area of Central Europe in unselected patients from Belarus diagnosed with ovarian cancer." (PMID 33478551, 2021). "In high-grade serous ovarian cancer, BRCA1/BRCA2 gene mutations are important players in the HR pathway and account for 20% of patients with ovarian cancer with BRCA1/BRCA2 somatic or germline mutations." (PMID 34712221, 2021). "Individuals with hereditary mutations in BRCA1 and BRCA2 are predisposed to a higher risk of breast or ovarian cancer." (PMID 33674888, 2021). "Pathogenic or likely pathogenic germline BRCA1 or BRCA2 variants are present in 18% of ovarian cancer cases." (PMID 34711195, 2021). "The aim of this audit was to evaluate the usefulness and serviceability of testing for pathogenic mutations in BRCA1 or BRCA2 (BRCA1/2) genes in ovarian cancer (OC) patients." (PMID 33808557, 2021). "The use of PARP inhibitors has been approved for treatment in BRCA1 and BRCA2 mutated breast and ovarian cancers, and for therapy in platinum sensitive ovarian cancer patients with defective BRCA1/2 genes." (PMID 34639169, 2021).
ovarian carcinoma (continued). "Analysis of the mutation distribution among breast and ovarian cancer families identified several regions along the BRCA2 gene with high risks." (PMID 34440403, 2021). "The genes BRCA1 e BRCA2 are the strongest recognized genetic risk factors for epithelial ovarian cancer, although some studies show an association with the AXIN2 gene in several cancers, including the ovarian one." (PMID 34378652, 2021). "BRCA1 and BRCA2, both of which help maintain genomic stability and are significantly mutated in ovarian cancer, directly interact with RAD51." (PMID 33952262, 2021). "(EGFR and ALK in NSCLC, BRCA1 and BRCA2 in breast and ovarian cancer and homologous recombinant deficiency in prostate cancer)." (PMID 35047063, 2021). "A BRCA1 or BRCA2 gene mutation was detected in 54 of the 214 (25.2%) women affected with epithelial ovarian cancer." (PMID 33478551, 2021). "Mutations in DNA repair genes BRCA1 and BRCA2 contribute to heredity to ovarian cancer and accordingly increase the genomic instability." (PMID 34721577, 2021). "Nevertheless, BRCA1 carriers showed worse DFS, mostly due to higher rates of second primary malignancies (predominantly breast and ovarian cancers) as compared to BRCA2-mutated patients." (PMID 33579978, 2021). "PALB2, a partner and localizer of BRCA2, is a Fanconi anemia group protein (FANCN), which permits stable intranuclear localization and accumulation of BRCA2 and can cause pancreatic, breast, and ovarian cancer." (PMID 33413558, 2021). "PEO1 cell line carries a nonsense mutation that generates a truncated BRCA2 form incapable of HR, reflecting BRCA2-mutated ovarian cancers." (PMID 34956861, 2021). "Many of these cases have been attributed to germline mutations in BRCA1 and BRCA2 genes, which is a frequent molecular event in women with the most lethal and prevalent type of epithelial ovarian cancer, high grade serous ovarian carcinoma (HGSOC)." (PMID 34898566, 2021). "Women with pathogenic BRCA1 and BRCA2 mutations possess a high risk of developing breast and ovarian cancer." (PMID 34090422, 2021). "To demonstrate the power of our approach, here, we describe a detailed single-cell-level analysis of an ovarian cancer patient we found to exhibit constitutional somatic mosaicism of a pathogenic BRCA2 mutation." (PMID 34068254, 2021). "PEO1 is a BRCA2 germ-line deficient ovarian cancer cell line derived from a patient with a poorly differentiated serous adenocarcinoma." (PMID 33919707, 2021). "Our finding that BRCA2 mutations were significantly more frequent in the GR group is in accordance with evidence that mutations in BRCA1 and especially BRCA2, confer chemo‐sensitivity in ovarian cancer." (PMID 33811746, 2021). "Our results also show that BRCA2 mutation carriers had a significantly more first- and second-degree relatives with BC and ovarian cancer." (PMID 34575694, 2021). "The mechanisms driving the differential association between BRCA1 and BRCA2 mutations with progression and survival in breast and ovarian cancers are not completely understood." (PMID 33525353, 2021). "Mutations in BRCA1 or BRCA2 genes account for the majority of hereditary breast and ovarian cancers." (PMID 35008272, 2021). "A recent study, focusing on men only, also reported that BRCA2 mutations were associated with family history of breast/ovarian cancer." (PMID 34575694, 2021). "BRCA2 mutation carriers had significantly more first- and second-degree relatives with breast and ovarian cancer." (PMID 34575694, 2021). "Although, based on our findings and previously published data, the BRCA2 c.9976A>T variant alone probably cannot be considered as a risk factor for breast and ovarian cancer, it seems to be associated with other cancer types." (PMID 33672545, 2021). "Pathogenic variants in the BRCA1 and BRCA2 genes are associated with about 20% of familial breast and ovarian cancers." (PMID 33319336, 2021).